POTEJ (POTE ankyrin domain family member J)
Synonyms: POTE2beta
Tractability: PROTAC: ubiquitination databases record sites on it.
Gene: Protein-coding gene on chromosome 2 (130,611,440 to 130,658,037, forward strand). Ensembl gene ENSG00000222038.
Gene Ontology:
Molecular function: protein kinase binding; structural constituent of postsynaptic actin cytoskeleton
Biological process: axonogenesis; cell motility; postsynaptic actin cytoskeleton organization
Cellular component: extracellular exosome; extracellular region; actin cytoskeleton; actin filament; axon; cytoplasm; membrane; NuA4 histone acetyltransferase complex; synapse
Genetic constraint (gnomAD): Loss-of-function variants: 9 observed, 19.91 expected, observed/expected ratio (o/e) 0.45, 90% interval 0.27 to 0.79. The synonymous counts are far from expectation, so gnomAD's model fits this gene poorly and the ratio says little. Missense variants: 269 observed, 409.6 expected, observed/expected ratio (o/e) 0.66, 90% interval 0.59 to 0.73. Synonymous variants: 99 observed, 139.44 expected, observed/expected ratio (o/e) 0.71, 90% interval 0.6 to 0.84.
Homologues: Paralogues in human: POTEI (99% identical), POTEE (97% identical), POTEF (97% identical), POTEB3 (46% identical), POTEB (46% identical), POTEB2 (46% identical), POTED (45% identical), POTEC (43% identical), POTEG (41% identical), POTEH (41% identical), POTEM (41% identical), POTEA (34% identical), and 2 more.
Diseases named in the same sentence as POTEJ in open-access papers:
POTEJ is named in the same sentence as 1 disease in open-access papers, as found by Europe PMC text mining. Sharing a sentence is not in itself a finding about the gene and the disease. The quoted sentences say what the papers report.
male infertility (1 paper, 2025). The inability of the male to effect fertilization of an ovum after a specified period of unprotected intercourse. "Most of the top 60 genes are poorly characterized, and several have been recently linked to human male infertility, including C2orf78, POTEJ, and PROK2." (PMID 41282076, 2025).